SEMA3C (semaphorin 3C)
Diseases named in the same sentence as SEMA3C in open-access papers (continued):
Sharing a sentence is not in itself a finding about the gene and the disease.
tumor (continued). "We have found that SEMA3C ASO treatment resulted in reduced levels of the endothelial marker CD31 in LNCaP xenografts post‐castration, suggesting that reduced tumor growth may in part be mediated by anti‐angiogenic effects of SEMA3C inhibition." (PMID 29348142, 2018). "The association between SEMA3 gene expressions and tumor stemness score as well as with the drug sensitivity score indicated that SEMA3A, SEMA3C, and SEMA3F may mainly play tumor promotor roles during tumorigenesis as they are positively associated with tumor stemness and drug resistence scores." (PMID 32241267, 2020). "SEMA3C exerts its inhibitory effect especially on ECs in immature vessel sprouts, as these markedly express NRP1 and PlexinD1; thus, specific plexin D1 ligands may be useful to inhibit tumor angiogenesis." (PMID 30717262, 2019). "Moreover, anti-tumorigenic and anti-angiogenic effects of NaVP in ovo were enhanced in the presence of Sema3C overexpression, where the tumor cells placed on CAM failed to adhere to its surface." (PMID 31726800, 2019). "Interestingly, although the rest of SEMA3 family members showed significant negative correlation with tumour stem-cell-like features measured by mRNA (RNAss) and DNA methylation (DNAss), expression of SEMA3A, SEMA3C, and SEMA3F were not significantly correlated with RNAss." (PMID 32241267, 2020).
cancer (53 papers, 2011 to 2026). A tumor composed of atypical neoplastic, often pleomorphic cells that invade other tissues. "Specifically, the elucidated interplay between KLF6, TAF6L and FOSL2, along with their regulatory influences on SEMA3C and the Wnt-β-catenin pathway, enhancing our understanding of the complex networks underlying cancer drug resistance." (PMID 40082673, 2025). "We found that FOSL2 collaborates with KLF6 to regulate the expression of SEMA3C, a protein that has been implicated in cancer progression." (PMID 40082673, 2025). "Elevated expression and activity of SEMA3C have been associated with increased cancer cell invasion and adhesion." (PMID 39408230, 2024). "SEMA3C is a secreted member of the semaphorin family of extracellular signaling proteins that has been implicated in various cancers including prostate, breast, gastric, lung, and pancreatic cancer, as well as glioblastoma." (PMID 38528115, 2024). "MEGM DEGs are mainly associated with the topics ‘cancer’, ‘neuro’ and ‘eye & retina’ or two combined topics like ‘cancer and neuro’ (SEMA3C, ROR1, EPHA7, GDNFR) or ‘eye & retina and neuro’ (PRDM8, CRYBG3)." (PMID 39695086, 2024). "For example, increased expression of SEMA3C associated with increased cancer cell sensitivity to Irofulven and Ibrutinib, and SEMA3F associated with Aminoflavone." (PMID 32241267, 2020). "The different oncogenic processes that SEMA3C is involved in have been reviewed previously; the following discussion is meant to build on those findings by highlighting the different cancer types that SEMA3C is implicated in." (PMID 30759745, 2019). "Among the class 3 semaphorins, SEMA3C is notable because its expression is most consistently associated with poor prognosis in a wide spectrum of cancers." (PMID 30759745, 2019). "The list of cancers that SEMA3C is implicated in has steadily grown and now includes gastric, lung, liver, breast, gynecological, prostate, pancreatic and brain." (PMID 30759745, 2019). "In cancer, SEMA3C and its receptors are often highly expressed and associated with invasion and metastasis." (PMID 30717262, 2019). "Elucidation of the differing molecular targets and signalling pathways underlying the seemingly contradictory roles of SEMA3C would be very valuable in future evaluations of which cancers would benefit most from SEMA3C inhibitors while avoiding harm in others." (PMID 30759745, 2019). "Sema3C and its receptors are frequently overexpressed in cancer and are associated with invasion and metastasis." (PMID 29642487, 2018). "The semaphorin family of proteins are implicated in virtually every Hallmark of Cancer29 and SEMA3C specifically is frequently associated with cancer growth." (PMID 28904399, 2017). "Notably, NRP1, a known co-receptor of Sema3C, has been repeatedly implicated in cancer cell resistance to therapy." (PMID 33537086, 2021). "Clarifying the roles of SEMA3C and the associated downstream pathways in these and other cancers may broaden the relevance of SEMA3C inhibitors as therapeutic agents." (PMID 30759745, 2019). "Remarkably, the regulatory networks governing semaphorin expression are largely unknown despite the fact that SEMA3C and its kin are heavily implicated in cancer." (PMID 28038451, 2017). "Due to its role in neurodevelopmental processes which are frequently dysregulated in cancer, inhibiting SEMA3C signalling is proposed as therapeutic strategy to improve cancer control." (PMID 38384455, 2024). "Semaphorin 3C (SEMA3C) is a secreted autocrine growth factor that drives growth and treatment resistance of prostate and other cancers and is known to be regulated by both AR and FOXA1." (PMID 38528115, 2024). "SEMA3C enhances peritoneal dissemination by regulating putative cancer stemness and Gem resistance and activates phosphorylation of the Akt/mTOR pathway via c-Met." (PMID 37537633, 2023).
cancer (continued). "Semaphorin 3C (SEMA3C) expression has been demonstrated to be unfavourable in terms of prognosis across various cancers, including breast." (PMID 37685898, 2023). "Most importantly, some studies have revealed that the functions of Plexins in cancers are regulated by semaphorins, including Sema3C, Sema4D, and Sema5A." (PMID 37901456, 2023). "Our previous findings indicate that SEMA3C functions as a secreted soluble autocrine growth factor that drives cancer growth by transactivating multiple RTKs such as EGFR, HER2 and MET via Plexin B1." (PMID 37443749, 2023). "Significantly, overexpression of the KRAS G12D in cultured cancer cells was found to increase the SEMA3C expression." (PMID 35785187, 2022). "Dysregulation of semaphorin 3A or semaphorin 3C has been implied for cardiovascular disease and various cancers." (PMID 34270956, 2021). "This was reminiscent of the BMP response and condensation gradients described previously and in agreement with the established role of Sema3c in the regulation of cohesive/metastatic balance in several cancers." (PMID 32105214, 2020). "SEMA3C is involved in endothelial cell apoptosis, it inhibits pathological angiogenesis and it promotes invasion and metastasis in cancers." (PMID 32766254, 2020). "SEMA3C presents an attractive target as an anti-cancer therapy due to its cited involvement in numerous biological processes that surround cancer etiology and progression." (PMID 30759745, 2019). "Molecular territories delineated by secreted semaphorins provide directional cues for cell movement which links SEMA3C to invasion & metastasis—one of the key hallmarks of cancer." (PMID 30759745, 2019). "SEMA3C continues to receive attention for both its roles in development and for its involvement in cancer biology." (PMID 30759745, 2019). "This would indicate that the opportune time to inhibit SEMA3C would be concurrently with first-line therapies in order to achieve complete cancer remission." (PMID 30759745, 2019). "It is hoped that this report stimulates scholarly pursuits into considering SEMA3C as a therapeutic target for treatment of prostate and other cancers." (PMID 30759745, 2019). "SEMA3C has been discussed largely for its pro-tumorigenic roles in a multitude of cancers including prostate, pancreas, brain, breast, and stomach." (PMID 30759745, 2019). "While reviews of the semaphorins, semaphorins in cancer, and semaphorins as targets of therapy are available and detailed elsewhere, this report surveys the potential in targeting SEMA3C in cancer." (PMID 30759745, 2019). "We have recently found that SEMA3C drives cancer growth by transactivating multiple receptor tyrosine kinases including EGFR, HER2 and MET via Plexin B1." (PMID 30759745, 2019). "One member, Semaphorin 3C (SEMA3C), has been shown to drive a number of oncogenic programs, correlate inversely with cancer prognosis, and promote the progression of multiple different cancer types." (PMID 30759745, 2019). "As alluded to earlier, SEMA3C is thought to contribute to the progression of PCa by promoting cancer recurrence." (PMID 30759745, 2019). "One member, Sema3C protein, has been shown to be involved in the development of gastric, breast, pancreatic, brain, prostate, and other cancers, as well as in maintenance of cancer stem-like cells (CSCs)." (PMID 31726800, 2019). "Here we discuss the possibility of inhibiting SEMA3C as a cancer treatment modality and provide prospective molecular approaches for inhibiting SEMA3C such as biologics, small molecules, monoclonal antibodies, and antisense oligonucleotides." (PMID 30759745, 2019). "SEMA3C expression has been correlated with worse prognosis in other cancers, but the relative contribution of SEMA3C signaling for these cancers remains to be determined." (PMID 30759745, 2019). "Collectively, these data suggest that autocrine SEMA3C drives cancer cell growth and survival via RTK pathway activation." (PMID 29348142, 2018).
cancer (continued). "Cleavage of Sema3C by the metalloproteinase ADAMTS1 facilitates its release from the extracellular matrix to bind its receptors on cancer cells to promote cell migration." (PMID 29642487, 2018). "In search of novel targets associated with expression of PTEN, a gene that is frequently mutated in advanced PCa, DNA microarray profiling identified SEMA3C among the top three most differentially expressed genes between PTEN+ vs. PTEN−/− cancer cells." (PMID 29348142, 2018). "It would be interesting to explore the role of Sema3C in therapeutic resistance in other cancer types." (PMID 29642487, 2018). "In this review, we will discuss the role of Semaphorin 3C (Sema3C) as an example of one axonal guidance cue that drives cancer progression." (PMID 29642487, 2018). "In fact, Sema3c, Id1, Cxcl1 and Ctgf, which are upregulated in a variety of cancer types, were downregulated upon Pdrg1 silencing." (PMID 27548429, 2016). "Recent studies suggested involvement of Sema3C (semaphorin 3C) protein in tumorigenesis and metastasis in a number of cancers." (PMID 26032848, 2015). "Previous studies have demonstrated that Sema3C promotes cell migration of axons, neural crest cells, and metastatic cancer cells." (PMID 22242143, 2011). "Finally, SEMA3C was identified as an effective biomarker reflecting cancer stage and microvessel density." (PMID 41637545, 2026). "Our findings suggest that TQ modulates Wnt signaling by altering the expression of its core components (WNT7B and WNT6) and regulators (PDE2A and Sema3C), thereby potentially downregulating this oncogenic pathway and contributing to its anti-cancer mechanism in vitro." (PMID 39874307, 2025). "Furthermore, SEMA3C and its receptor, Plexin B1, drive cancer growth by transactivating multiple receptor tyrosine kinases including EGFR, HER2 and MET20,29–31." (PMID 38528115, 2024). "SEMA3C promotes cancer cell survival by regulating autophagy and affecting the TME immune response." (PMID 37537633, 2023). "For SEMA3A, SEMA3C, and SEMA7A as well as the semaphorin receptor neuropilin, there was a clear trend where the expression above the cutoff was associated with worse survival for all three cancers." (PMID 37719704, 2023). "Importantly, our investigation revealed that SEMA3C activates MAPK and AKT pathways, which are essential for sustaining cancer cell proliferative signaling, a fundamental hallmark of cancer, making it a potential therapeutic target." (PMID 37443749, 2023). "SEMA3C also can take part in the migration or metastasis of cancer cells." (PMID 35785187, 2022). "SEMA3C also plays an important role in the maintenance of cancer stem-like cells." (PMID 35785187, 2022). "SEMA3C and its receptors continue to draw great attention in the context of numerous cancer." (PMID 30759745, 2019). "Finally, we discuss important considerations for the inhibition of SEMA3C as a cancer therapeutic agent." (PMID 30759745, 2019). "Inhibitors of SEMA3C could also be combined with other cancer therapeutics including RTK inhibitors, taxanes, and antagonists of the AR axis in the case of PCa, to assess the possibility of synergy." (PMID 30759745, 2019). "These seemingly opposing SEMA3C-induced effects are likely due to the different forms of SEMA3C examined (e.g., non-cleavable, cleavable, or truncated forms) as well as the utilization of different cancer models and biological systems." (PMID 30759745, 2019). "We further evaluated the effect of SEMA3C knock-down on cancer cell proliferation in vivo." (PMID 31649890, 2019). "In many tumors, Sema3C appears to promote cancers and in particular CSC survival." (PMID 29642487, 2018). "Sema3C is a secreted semaphorin that plays an important role in the maintenance of cancer stem-like cells, promotes migration and invasion, and may facilitate angiogenesis." (PMID 29642487, 2018). "Sema3C plays an oncogenic role in many different types of cancers." (PMID 29642487, 2018).
cancer (continued). "Sema3C is identified as a drug resistance gene in cancer cell lines." (PMID 29642487, 2018). "Furthermore, we show that SEMA3C drives activation of distinct combinations of RTK signaling pathways depending on the RTK expression profile of the cancer cells and on the context of cell type." (PMID 29348142, 2018). "Semaphorin 3C (SEMA3C) is a secreted signaling protein with roles in nervous system and cardiac development but can also drive cellular growth and invasive characteristics in multiple cancers including PCa." (PMID 28038451, 2017). "SEMA3C-induced upregulation of EGFR could have profound implications in cancer development and could underpin our findings and those of studies involving semaphorins elsewhere." (PMID 28904399, 2017). "Despite numerous findings that implicate SEMA3C in cancer progression, regulatory mechanisms governing its expression remain largely unknown." (PMID 28038451, 2017). "This propensity for motility may be especially important in CRPC where elevated SEMA3C expression may confer cancer cells with invasive phenotypes that contribute to metastasis." (PMID 28038451, 2017). "Additionally, genes normally upregulated in several types of cancer cells (Sema3c, Id1, Cxcl1, Ctgf) appear downregulated by Pdrg1 silencing." (PMID 27548429, 2016). "It has been shown, for example, that Sema3C is highly expressed in several human cancer types." (PMID 26032848, 2015). "SEMA3C may contribute to drug-induced resistance of cancer cells." (PMID 38384455, 2024). "In addition to their role in ECM construction, myCAFs may also enhance the stemness and proliferation of cancer cells by overexpressing secreted factors, including SEMA3C, POSTN, and CXCL6." (PMID 35986392, 2022). "We found that SEMA3B, SEMA3D, SEMA3E, and SEMA3G were all negatively associated with cancer-stem like features, but SEMA3A, SEMA3C, and SEMA3F were positively correlated with DNAss, which indicates that SEMA3s may associate with cancer cell sensitivity or resistance to chemotherapy treatment." (PMID 32241267, 2020). "Further to this, considering SEMA3C levels correspond with the malignant phenotype, cancer stage, cancer grade, and other important clinical parameters in multiple cancer types, it is possible that circulating SEMA3C status may represent a diagnostic or prognostic tool." (PMID 30759745, 2019). "Outside of cancer, whilst primarily noted for their participation in the development of the nervous system, research has also established the importance of SEMA3C and its receptors in cardiovascular, retinal and renal development, as well as chondrogenesis, and alveolar growth and repair." (PMID 30759745, 2019). "Therapeutic strategies that inhibit Sema3C signaling may improve cancer control." (PMID 29642487, 2018). "Whether other semaphorins cooperate with or compete with Sema3C in cancer is not well understood." (PMID 29642487, 2018). "Taking into account this functional background of Sema3C, perhaps it is not surprising to witness an increasing number of studies showing that aberrant expression levels of this protein is associated with a number of cancer phenotypes." (PMID 26032848, 2015). "In contrast to SEMA3A, SEMA3C, and SEMA3F, the rest of the SEMA3 family members showed prominent down-regulation and they all negatively correlated with cancer stem-cell-like features (RNAss and DNAss) across cancer types." (PMID 32241267, 2020). "SEMA3A, SEMA3D, and SEMA3E showed relatively lower level of expression averaged across all cancer types compared to the rest of the SEMA3 family members.i.e., SEMA3B, SEMA3C, SEMA3F and SEMA3G, where SEMA3F had the highest expression." (PMID 32241267, 2020). "Nevertheless, SEMA3A, SEMA3C, and SEMA3F primarily showed up-regulated expression, and the rest of the SEMA3s mainly showed down-regulated expression in the 16 tested cancer types." (PMID 32241267, 2020).
cancer (continued). "The link between SEMA3C and EMT and cancer stem cells punctuates the importance in exploring SEMA3C or its receptors as potential cancer targets." (PMID 30759745, 2019). "SEMA3C expression levels increase in castration‐resistant prostate cancer (CRPC), where it functions to promote cancer cell growth and resistance to androgen receptor pathway inhibition." (PMID 29348142, 2018). "The overexpression of SEMA3C and SEMA3E in cancer cells correlates with multidrug resistance and increased metastatic capability." (PMID 26294325, 2015). "Importantly, RNA-seq indicated DNAJC10 downregulates CAMs-related genes such as ITGAV, SEMA3C, DPP4, and ITGA1, which promote cancer cell migration and invasion." (PMID 41191192, 2025). "Moreover, we discovered that FOSL2 upregulates SEMA3C and c-Myc in 5-FU-resistant HCT15 cells through the canonical Wnt–β-catenin signaling pathway, a critical pathway known to drive cancer growth and survival." (PMID 40082673, 2025). "Furthermore, Heatmap analysis showed DNAJC10 overexpression reduced transcription of CAMs related genes such as ITGAV, SEMA3C, DPP4, and ITGA1, which are reported to enhance cancer cell migration and invasion." (PMID 41191192, 2025). "These regions contain important cancer-related genes including TRIM28, SEMA3C, NOTCH1, and FAT1." (PMID 34168152, 2021). "In fact, the expression of Sema3c in the cardiac NCC is required for their convergence to the endocardium and was also shown to promote the aggregation of cardiac NCC in primary cultures as well as in cancer cells in vivo." (PMID 32105214, 2020). "Among the 7 SEMA3 gene members, expression levels of SEMA3A and SEMA3C, SEMA3C and SEMA3F showed the highest correlation across all 31 cancer types, suggesting they may share some common functions." (PMID 32241267, 2020). "Similar to SEMA3C’s role in mediating intrinsic resistance of PCa to targeted RTK therapies, SEMA3C may also play a role in facilitating acquired resistance of cancer to RTK targeted agents." (PMID 30759745, 2019). "Finally, our study revealed that SEMA3 genes, especially SEMA3C and SEMA3F may contribute to drug induced cancer cell resistance." (PMID 32241267, 2020). "Thus, the ability of SEMA3C to simultaneously transactivate multiple RTKs such as EGFR, HER2 and MET could facilitate the switch of primary dependency of cancer growth from one RTK pathway to another." (PMID 30759745, 2019). "Notably absent are inhibitors of SEMA3C since the significance of SEMA3C in cancer is only just becoming increasingly recognized." (PMID 30759745, 2019). "Thus, it is interesting to postulate whether SEMA3C’s ability to coordinately activate multiple RTK pathways may play a role in the setting of acquired resistance to RTK-targeted therapies in lung, head and neck, breast, colon and other cancers." (PMID 30759745, 2019).